TRIM28 (tripartite motif containing 28)
Diseases named in the same sentence as TRIM28 in open-access papers (continued):
Sharing a sentence is not in itself a finding about the gene and the disease.
ovarian carcinoma (11 papers, 2017 to 2024). A malignant neoplasm originating from the surface ovarian epithelium. "The expression level of TRIM28 was also found to be elevated in ovarian cancer samples, and this elevation was linked to aggressive clinical characteristics." (PMID 39534556, 2024). "In ovary cancer, TRIM28 high expression was an independent predictor for patients with ovarian cancer." (PMID 33778494, 2021). "The analysis of TCGA datasets of ovarian cancer indicated a negative correlation between SETDB1 or TRIM28 and CD274 expression (encoding PD-L1 immune checkpoint)." (PMID 39519018, 2024). "Consistent with the unpaired t test analysis, Mann–Whitney U test comparing the median also shows significant differences between High and Low TRIM28 expression groups of endometrial and ovarian cancer patients (P < 0.0001 for endometrial cancer, P = 0.0114 for ovarian cancer)." (PMID 37070200, 2023). "Moreover, high expression of TRIM28 served as an independent predictor for ovarian cancer patients." (PMID 39534556, 2024). "Furthermore, TRIM28 high expression was an independent predictor for ovarian cancer patients." (PMID 28851455, 2017). "The expression level of TRIM28 was also higher in ovarian cancer samples than in matched non-tumor ovarian tissues and correlated with aggressive clinical features." (PMID 28851455, 2017).
colorectal cancer (10 papers, 2018 to 2026). A primary or metastatic malignant neoplasm that affects the colon or rectum. "In this study, we have therefore taken a differential proteomic approach to investigate TRIM28-associated molecular pathway activation directly in colorectal cancer tissue compartments." (PMID 29631612, 2018). "We have previously shown that high TRIM28 expression ratios between stromal and epithelial compartments of colorectal carcinomas are associated with poor patient survival and disease recurrence." (PMID 29631612, 2018). "In addition, our findings demonstrate that knockout of TRIM28 in Caco2 colorectal cancer cells is associated with a pronounced upregulation of immune checkpoint molecules CD47 and CD24 on both mRNA and protein levels, particularly in clones exhibiting concurrent downregulation of CD133." (PMID 41303350, 2025). "First, we demonstrated that TRIM28 knockout in Caco2 colorectal cancer cells results in a significant reduction in proliferation rate, as evidenced by delayed monolayer formation during live-cell imaging." (PMID 41303350, 2025). "In this study, we performed a detailed molecular and functional analysis of Caco2 colorectal cancer cell clones with individual knockouts of CD133 or TRIM28." (PMID 41303350, 2025). "Together, these results underscore the central role of TRIM28 in regulating proliferation and migratory phenotypes in colorectal cancer cells and establish a transcriptional foundation for further investigation of its downstream effectors." (PMID 41303350, 2025). "In summary, our study highlights TRIM28 as a multifaceted regulator of colorectal cancer cell behavior, integrating control over proliferation, chemoresistance, and immune evasion." (PMID 41303350, 2025). "We have previously shown that stromal expression of TRIM28 is a marker of disease relapse and poor survival in colorectal cancer." (PMID 29631612, 2018). "TRIM28 is a marker of disease relapse and poor survival in colorectal cancer that engages different molecular mechanisms in the context of its expression within the tumor microenvironment." (PMID 29631612, 2018). "We have previously shown that TRIM28 is overexpressed in colorectal cancer and that its stromal expression is an independent marker of disease relapse and patient survival." (PMID 29631612, 2018). "In this paper, we sought to further investigate how differences in expression patterns of TRIM28 in epithelial and stromal tissue compartments in colorectal cancer can influence patient survival." (PMID 29631612, 2018). "In addition, KRAS-mediated KAP1/TRIM28 sumoylation is also involved in the KRAS-driven transformation in colorectal cancer." (PMID 32210733, 2020). "We have previously shown that the assessment of TRIM28 expression levels, when it encompasses epithelial and stromal tissue compartments, can serve as an independent marker of relapse and patient survival in colorectal cancer." (PMID 29631612, 2018). "Collectively, our findings indicate that targeting TRIM28 may exert complex effects on tumor–immune interactions through modulation of key checkpoint molecules, underscoring the need for further mechanistic studies to elucidate the role of TRIM28 in immune escape within colorectal cancer." (PMID 41303350, 2025). "Indeed, growth factor signaling via EGFR and downstream MAPK/PI3K cascades is a critical driver of cell proliferation and drug sensitivity in colorectal cancer, and its attenuation is consistent with the reduced responsiveness of TRIM28-KO cells to cytotoxic agents." (PMID 41303350, 2025).
colorectal cancer (continued). "In this study, we conducted a comparative molecular and functional study of Caco2 colorectal cancer cell clones with individual knockouts of either CD133, a widely used CSC surface marker, or TRIM28, an epigenetic regulator previously shown to modulate CD133 expression." (PMID 41303350, 2025). "Altogether, our results demonstrate that TRIM28, rather than CD133, functions as a central regulator of CSC-associated phenotypes in colorectal cancer." (PMID 41303350, 2025). "Our transcriptomic analysis revealed that TRIM28 knockout, but not CD133 depletion, induces substantial changes in gene expression in Caco2 colorectal cancer cells." (PMID 41303350, 2025).
liver cancer (9 papers, 2019 to 2026). An epithelial or non-epithelial malignant neoplasm that arises from the liver. "It is reported that TRIM28 is also correlated with immune infiltration in liver cancer that highlights an unnoticed function of TRIM28 in immune system." (PMID 37781084, 2023). "Recently, it has been demonstrated that the TRIM28-MAGE complex degrades FBP1 in liver cancer cells." (PMID 34440587, 2021). "Moreover, elevated levels of both mRNA and protein expression of TRIM28 were noted in tumor tissues from patients with liver cancer." (PMID 39534556, 2024). "It was demonstrated that liver cancer cell lines expressing TRIM28 were highly expressed." (PMID 36238495, 2022). "Fortunately, we have demonstrated that TRIM28 was highly expressed in liver cancer cells line." (PMID 36238495, 2022). "For example, in a mouse model of liver cancer TRIM28 opposes tumorigenesis." (PMID 31666584, 2019). "In addition, TRIM28 is involved in the regulation of immune‐related genes, and its interaction with HBX may help the virus to evade the host's immune system, leading to chronic infection and an increased risk of liver cancer." (PMID 39534556, 2024). "Our results indicated that the increased expression of TRIM28, TRIM37, TRIM45, and TRIM59 in liver cancer tissues likely plays a pivot role in HCC." (PMID 35142083, 2022). "Moreover, FBP1 is post-transcriptionally modulated by the MAGE-tripartite motif-containing 28 (TRIM28) complex and USP44 in PDAC and liver cancers." (PMID 34440587, 2021). "It has not been studied whether TRIM28 plays a role in human liver cancer, particularly in LIHC." (PMID 36238495, 2022).
non-small cell lung carcinoma (9 papers, 2014 to 2024). A group of at least three distinct histological types of lung cancer, including non-small cell squamous cell carcinoma, adenocarcinoma, and large cell carcinoma. "However, little is known about TRIM28 expression and its role in the immune microenvironment of non-small cell lung cancer (NSCLC)." (PMID 37865804, 2023). "We found that Trim28 plays a role in TGF-β-induced EMT in non-small cell lung cancer cells." (PMID 24983967, 2014). "In non-small cell lung cancer (NSCLC) cell lines, Liu L demonstrated that the stable silencing of TRIM28 expression by a specific siRNA lentivirus vector significantly inhibited the growth and exerted obvious anti-tumor effects in nude mice." (PMID 30484263, 2019).
lung adenocarcinoma (8 papers, 2014 to 2023). A carcinoma that arises from the lung and is characterized by the presence of malignant glandular epithelial cells. "TRIM28 was upregulated in lung adenocarcinoma patients with low immune and stromal scores, and was associated with a poor prognosis." (PMID 33091876, 2020). "In previous work, we demonstrated that transcription factor Trim28 (Tripartite motif containing 28) plays a tumor-suppressor role in early-staged adenocarcinoma of the lung due to its ability to restrain transcription of cell cycle-regulating genes." (PMID 24983967, 2014). "The POU2F2 and TRIM28 co-expressed lncRNA landscape characterized here may shed light into normal biology and lung adenocarcinoma pathogenesis, and be valuable for discovery of biomarkers." (PMID 29127420, 2017). "To further investigate whether the therapeutic benefits of combined TRIM28 inhibition and anti-PD-1 extend to human NSCLC, we utilized a human lung adenocarcinoma cell line, H1299, in a humanized huHSC-NOG-EXL mouse model." (PMID 37865804, 2023). "In our previous work, we discovered that high Trim28 (Tripartite motif containing 28) proteins levels correlate with longer overall survival in early-staged lung adenocarcinoma patients, but not in late-staged patients." (PMID 24983967, 2014). "Thus, TRIM28 may worsen the TIME and prognosis of lung adenocarcinoma." (PMID 33091876, 2020).
bladder cancer (7 papers, 2020 to 2026). "In bladder cancer cells, phosphorylation of TRIM28 through mTORC1 induces hTERT gene transcription to promote cancer cell growth." (PMID 40519166, 2025). "Fourteen TRIM family proteins were associated with bladder cancer (tumor-promoting: TRIM9, TRIM25, TRIM26, TRIM28, TRIM29, TRIM59, TRIM65, and TRIM66; tumor-suppressive: TRIM19 and TRIM38)." (PMID 40723250, 2025). "To date, recent studies revealed that GABPB1L and TRIM28 had the potential to be the therapeutic target for TERT promoter mutation‐positive patients with glioblastoma and bladder cancer, respectively." (PMID 38769666, 2024). "TRIM24 and TRIM28 have emerged as key regulators of hTERT expression in bladder cancer." (PMID 39160596, 2024). "This complex regulatory interplay between TRIM28 and TRIM24 provides valuable insights into the mechanisms governing hTERT expression in bladder cancer." (PMID 39160596, 2024). "In bladder cancer, GABPA is involved in the recruitment of two transcriptional co-regulators of telomerase expression, namely, TRIM28 (tripartite motif containing 28) and TRIM24, to the mutant TERT promoter −124A." (PMID 38033865, 2023).
pancreatic cancer (7 papers, 2017 to 2025). "Furthermore, we showed that JQ1 stabilized FBP1 protein level by disrupting the interaction between FBP1 and TRIM28 in pancreatic cancer cells." (PMID 30201002, 2018). "According to studies, JQ1 disturbs the link between TRIM28 and FBP1, improving FBP1 protein levels, and FBP1 increases c-Myc degradation by blocking the MAPK pathway, making pancreatic cancer more sensitive to JQ1." (PMID 40100307, 2025). "JQ1 reduces the ubiquitination of FBP1 by disrupting the interaction between FBP1 and TRIM28, suggesting that JQ1 may be an ideal small molecule to increase FBP1 expression and inhibit pancreatic cancer." (PMID 40100307, 2025). "Pbk, Fastk, Cdk19, Adck5, Trim28, and Pfkp may be the regulatory genes for CD73 in pancreatic cancer." (PMID 37835536, 2023). "Pbk, Fastk, Cdk19, Adck5, Trim28, and Pfkp are the genes that may regulate CD73 in pancreatic cancer." (PMID 37835536, 2023). "Our findings in this study suggest that JQ1 increases FBP1 stability through disrupting the interaction between FBP1 and TRIM28, which suggest JQ1 might be an ideal small molecular to increase the FBP1 expression and repress pancreatic cancer." (PMID 30201002, 2018).
cervical cancer (6 papers, 2017 to 2023). A primary or metastatic malignant neoplasm involving the cervix. "In a study of cervical cancer, it was demonstrated that TRIM28 promoted the growth of cervical cancer cells by activating the mTOR signaling pathway." (PMID 33817325, 2021). "For example, Li F compared TRIM28 expression between cervical cancer and adjacent normal tissues, and detected significant elevation in TRIM28 expression levels in the cervical cancer tissues." (PMID 30484263, 2019). "The utilization of mTOR inhibitors could reduce TRIM28-induced cell proliferation, suggesting that it could be used as a potential therapeutic target for cervical cancer." (PMID 33817325, 2021). "TRIM28 also affected the mTOR signaling pathway, resulting in the growth of cervical cancer." (PMID 34722282, 2021). "They believed that TRIM28 played a pivotal role in cervical cancer cell proliferation and might serve as a potential therapeutic target." (PMID 30484263, 2019). "In cervical cancer, ZBRK1 can inhibit the transcription of TRIM28, thereby regulating the expression of metastasis-related genes." (PMID 36756159, 2023).
breast invasive carcinoma (5 papers, 2016 to 2025). "TRIM28 plays an increasingly crucial role in cancer, but its impact on BC, including breast invasive carcinoma, remains poorly understood." (PMID 38947392, 2024). "As a result, we observed that TRIM28 is highly expressed in breast invasive carcinoma tissues compared with the corresponding normal tissues and is correlated with metastatic / invasive progression." (PMID 38947392, 2024). "TRIM28 is also significantly differentially expressed in the TCGA breast invasive carcinoma (BRCA) gene expression profiles of more than 1000 patients compared with normal tissues (p < 1E-06)." (PMID 27845900, 2017). "High expression of TRIM28 might serve as a prognostic marker for long-term survival in triple-negative BC, advanced BC, or breast invasive carcinoma." (PMID 38947392, 2024). "Thus, TRIM28 might be a potentially valuable molecular target for forecasting the progression / prognosis of patients with breast invasive carcinoma." (PMID 38947392, 2024). "Although TRIM28 methylation in tumor tissues of breast invasive carcinoma is not significantly changed compared to the matched normal tissues, the expressions and methylation of TRIM28 are significantly reversely correlated." (PMID 38947392, 2024).
COVID-19 (5 papers, 2021 to 2025). A disease caused by infection with severe acute respiratory syndrome coronavirus 2. "Additionally, TRIM28 deficiencies have been correlated with severe pediatric COVID-19 cases." (PMID 37345956, 2023). "The TRIM28 gene significantly decreased in children with severe COVID-19 in comparison to children with mild infection in the blood samples." (PMID 36192760, 2022). "The effect of the TRIM28 gene in COVID-19 as a new disease seems to be interesting; therefore, this study aimed to evaluate the expression of the TRIM28 gene in the blood samples of patients with mild and severe COVID-19 infections." (PMID 36192760, 2022). "The RNA-sequencing analysis of transcriptional response to SARS-CoV-2 in cells, animal models, and lung tissue clinical samples of COVID-19 patients also showed a reduction in TRIM28 gene." (PMID 36192760, 2022). "Our results showed a meaningful reduction of TRIM28 in patients with COVID-19 in both studied groups and proposed a possible relationship between TRIM28 expression and the rate of COVID-19 severity." (PMID 36192760, 2022). "In COVID-19 children significant positive correlations were found between expressions of type I ISGs and TRIM28." (PMID 34299101, 2021). "TRIM-28-defective regulatory T cells fail to control autoimmune manifestations, whose increase in severe COVID-19 patients could thus be supported by the upstream downregulation of TRIM28." (PMID 34299101, 2021). "Positive correlations emerged between the transcriptional levels of type I and II IFNs, TRIM28, SETDB1, and HERVs in COVID-19 patients." (PMID 34299101, 2021). "The significant positive correlations between transcripts of IFN-I and IFN-II and of TRIM28 and SETDB1 suggest that the former may exert important regulatory functions on the transactivation of the latter in COVID-19 children." (PMID 34299101, 2021). "Briefly, our findings suggest that aberrant expressions of TRIM28 and SETDB1 in COVID-19 children may condition the evolution of the infection via their crucial regulatory functions on the immune system, from the innate response to the adaptive response." (PMID 34299101, 2021). "Despite the potential mutual interplays between TRIM28/SETDB1, HERVs, and SARS-CoV-2, no investigations have explored their activation in patients affected by COVID-19, but a recent report that has highlighted the higher expression of MSRV-env in adults." (PMID 34299101, 2021). "Despite the potential cross-talks between SARS-CoV-2 infection and TRIM28, SETDB1, and HERVs, information on their expressions in COVID-19 patients is lacking." (PMID 34299101, 2021).
embryonic carcinoma (5 papers, 2008 to 2019). "KAP1, TRIM28) is distinct in various differentiation pathways, induced in embryonal carcinoma cells." (PMID 31533340, 2019).
Parkinsonism (5 papers, 2016 to 2025). Characteristic neurologic anomaly resulting from degeneration of dopamine-generating cells in the substantia nigra, a region of the midbrain, characterized clinically by shaking, rigidity, slowness of movement and difficulty with walking and gait. "Using transgenic Drosophila tauopathy model and α-syn-overexpression-induced Parkinsonism mouse model confirmed that suppressing TRIM28 reduced the accumulation of pathogenic proteins α-syn and tau proteins in the nervous system." (PMID 35946309, 2022). "The results indicated an increase in TRIM28 gene expression, indicating the association of ZNF543 with TRIM28 in mediating parkinsonism." (PMID 37194005, 2023).
colon cancer (4 papers, 2012 to 2023). "TRIM28 was reported to inhibit autophagy through promoting degradation of AMPK-α1 in lung, breast, and colon cancer cells, which depends on MAGE family proteins as adaptors." (PMID 36935008, 2023).
Infertility (4 papers, 2020 to 2024). "One report reveals a new aspect of TRIM28 haploinsufficiency: a highly penetrant infertility phenotype observed in male mice heterozygous for TRIM28 (TRIM28Het)." (PMID 39534556, 2024). "Here, we report a new facet to TRIM28 haploinsufficiency, a remarkably penetrant infertility phenotype in heterozygous Trim28 (Trim28Het) male mice." (PMID 32302554, 2020). "In this study, we uncovered and characterized a Trim28 haploinsufficiency-induced infertility phenotype using conditional, constitutive, and inducible genetic approaches." (PMID 32302554, 2020). "Our study on TRIM28 reveals that heterozygous mice are viable but exhibit a premature infertility phenotype in male animals." (PMID 32302554, 2020).